HOXD4 (homeobox D4)
Description:
Sequence-specific transcription factor which is part of a developmental regulatory system that provides cells with specific positional identities on the anterior-posterior axis.
Synonyms: HOX4B; HHO.C13; HOX-5.1; HOX4; Hox-4.2
Tractability: No criterion of Open Targets' tractability assessment is met for any kind of drug.
Gene: Protein-coding gene on chromosome 2 (176,151,550 to 176,153,226, forward strand). Ensembl gene ENSG00000170166.
Subcellular location: Nucleus
Subcellular location (Human Protein Atlas): Nucleoplasm; Cell Junctions
Pathways (Reactome):
Developmental Biology: Activation of anterior HOX genes in hindbrain development during early embryogenesis
Gene Ontology:
Molecular function: DNA-binding transcription activator activity, RNA polymerase II-specific; protein binding; RNA polymerase II transcription regulatory region sequence-specific DNA binding; sequence-specific double-stranded DNA binding; DNA-binding transcription factor activity, RNA polymerase II-specific; RNA polymerase II cis-regulatory region sequence-specific DNA binding; DNA binding; DNA-binding transcription factor activity
Biological process: embryonic organ development; positive regulation of transcription by RNA polymerase II; anterior/posterior pattern specification; embryonic skeletal system morphogenesis; regulation of DNA-templated transcription
Cellular component: nucleoplasm; chromatin; nucleus
Genetic constraint (gnomAD): Loss-of-function variants: 15 observed, 23.6 expected, observed/expected ratio (o/e) 0.64, 90% interval 0.42 to 0.98. The upper end of that interval is the gene's LOEUF score, 0.98, which puts it in group 4 of 6, group 1 being the genes least tolerant of losing a copy. Missense variants: 350 observed, 360.58 expected, observed/expected ratio (o/e) 0.97, 90% interval 0.89 to 1.06. Synonymous variants: 176 observed, 164.67 expected, observed/expected ratio (o/e) 1.07, 90% interval 0.94 to 1.21.
Homologues: Orthologues: chimpanzee HOXD4 (99% identical), macaque HOXD4 (96% identical), dog HOXD4 (93% identical), rat Hoxd4 (93% identical), pig HOXD4 (93% identical), mouse Hoxd4 (92% identical), guinea pig HOXD4 (91% identical), rabbit HOXD4 (87% identical), tropical clawed frog hoxd4 (66% identical), zebrafish hoxd4a (61% identical). Paralogues in human: HOXC4 (53% identical), HOXA4 (52% identical), HOXB4 (51% identical), HOXB5 (36% identical), HOXA5 (36% identical), HOXC5 (33% identical), HOXB6 (31% identical), HOXA3 (31% identical), HOXA7 (31% identical), HOXB3 (31% identical), HOXA6 (30% identical), HOXD3 (30% identical), and 30 more.